MAP3K12 (mitogen-activated protein kinase kinase kinase 12)
Description:
Part of a non-canonical MAPK signaling pathway. Activated by APOE, enhances the AP-1-mediated transcription of APP, via a MAP kinase signal transduction pathway composed of MAP2K7 and MAPK1/ERK2 and MAPK3/ERK1. May be an activator of the JNK/SAPK pathway.
Synonyms: DLK; ZPK; MUK; ZPKP1; MEKK12; HP09298
Tractability: Small molecule: a drug acting on it is in phase 2 or 3 trials; a structure with a bound ligand is known; a high-quality ligand is known; it belongs to a druggable protein family. Antibody: its Gene Ontology location is reachable by antibodies, with high confidence; UniProt places it where antibodies can reach, with medium confidence; the Human Protein Atlas places it where antibodies can reach. PROTAC: it is named in the literature on targeted protein degradation; its protein half-life has been measured; a small molecule that binds it is known.
Target class: STE protein kinase group; Enzyme; Kinase; Protein Kinase
Chemical probes: GNE-3511 (high quality), IACS-52825 (high quality)
Safety:
Unwanted effects reported when the protein is acted on. In parentheses: how it was acted on, where the effect was seen, and who reports it.
cardiac arrhythmia (cardiovascular system; source: Lamore et al. (2017))
Gene: Protein-coding gene on chromosome 12 (53,479,669 to 53,500,063, reverse strand). Ensembl gene ENSG00000139625.
Subcellular location: Cytoplasm; Cell membrane
Subcellular location (Human Protein Atlas): Nucleoplasm; Plasma membrane
Gene Ontology:
Molecular function: protein binding; protein kinase binding; protein homodimerization activity; protein kinase activity; protein serine kinase activity; protein serine/threonine kinase activator activity; protein serine/threonine kinase activity; ATP binding; MAP kinase kinase kinase activity
Biological process: positive regulation of DNA-templated transcription; positive regulation of ERK1 and ERK2 cascade; protein phosphorylation; intracellular signal transduction; JNK cascade; post-translational protein modification; protein autophosphorylation
Cellular component: cytoplasm; cytosol; membrane; plasma membrane; axon; growth cone
Genetic constraint (gnomAD): Loss-of-function variants: 14 observed, 88.49 expected, observed/expected ratio (o/e) 0.16, 90% interval 0.1 to 0.25. The upper end of that interval is the gene's LOEUF score, 0.25, which puts it in group 1 of 6, group 1 being the genes least tolerant of losing a copy. Missense variants: 761 observed, 1,138.9 expected, observed/expected ratio (o/e) 0.67, 90% interval 0.63 to 0.71. Synonymous variants: 456 observed, 453.72 expected, observed/expected ratio (o/e) 1, 90% interval 0.93 to 1.09.
Homologues: Orthologues: chimpanzee MAP3K12 (99% identical), dog MAP3K12 (98% identical), guinea pig MAP3K12 (98% identical), rabbit MAP3K12 (97% identical), mouse Map3k12 (96% identical), rat Map3k12 (96% identical), macaque MAP3K12 (95% identical), pig MAP3K12 (94% identical), tropical clawed frog map3k12 (64% identical), zebrafish map3k12 (64% identical), Drosophila melanogaster wnd (39% identical), Caenorhabditis elegans dlk-1 (29% identical). Paralogues in human: MAP3K13 (54% identical), MAP3K9 (26% identical), MAP3K21 (25% identical), MAP3K10 (24% identical), MAP3K11 (23% identical), MAP3K20 (14% identical), TNNI3K (13% identical), BRAF (12% identical), TESK2 (12% identical), ARAF (12% identical), LRRK2 (11% identical), RIPK1 (11% identical), and 11 more.
Diseases named in the same sentence as MAP3K12 in open-access papers:
MAP3K12 is named in the same sentence as 20 diseases in open-access papers, as found by Europe PMC text mining. Sharing a sentence is not in itself a finding about the gene and the disease. The quoted sentences say what the papers report.
prostate carcinoma (6 papers, 2019 to 2025). A carcinoma that arises from epithelial cells of the prostate gland. "Previously MAP3K12 has been associated with prostate cancer, and regulation of MAP3K12 by miRNAs could suppress prostate cancer progression." (PMID 39809819, 2025). "In prostate cancer, MAP3K12 exhibited a positively regulatory effect on the metastasis of tumor cells." (PMID 34881275, 2021). "AHR suppresses the viability and migration of human prostate cancer LNCaP cells, and plays pivotal role in cancer by modulating the downstream expression of Mitogen-Activated Protein Kinase Kinase Kinase 12 (MAP3K12)." (PMID 30972102, 2019).
Alzheimer disease (2 papers, 2021 to 2024). A progressive, neurodegenerative disease characterized by loss of function and death of nerve cells in several areas of the brain leading to loss of cognitive function such as memory and language. "The dual leucine zipper kinase (DLK) alias mitogen-activated protein 3 kinase 12 (MAP3K12) has gained much attention in recent years due to its involvement in several neurodegenerative diseases such as amyotrophic lateral sclerosis (ALS), Parkinson’s disease and Alzheimer’s disease, and glaucoma." (PMID 38391946, 2024).
autism (1 paper, 2016). Persistent deficits in social interaction and communication and interaction as well as a markedly restricted repertoire of activity and interest as well as repetitive patterns of behavior. "Interestingly, microdeletions and microduplications that include Dlk/MAP3K12, a likely Fbxo45 ubiquitination target, also result in intellectual disability and autism." (PMID 27008623, 2016).
breast tumors (1 paper, 2008). "In this way, evaluation of genes with somatic point mutations in breast tumors as compiled in the COSMIC database (release v36) placed MAP3K12 at the top of the combined rank, which reinforces the putative involvement of the MAPK signaling pathway and supports MAP3K12 as a likely candidate." (PMID 19094230, 2008).
cyst (1 paper, 2011). A sac-like closed membranous structure that may be empty or contain fluid or amorphous material. "We identified changes in gene expression related to cyst growth such as components of MAPK (e.g. Map3k12, Fgf10, Prkcb, Traf2) and TGF-β (e.g. Pitx2) signaling that were up-regulated in the Pkd1-/- animals." (PMID 21518438, 2011).
malignant pleural mesothelioma (1 paper, 2025). A malignant neoplasm that arises from mesothelial cells in the pleura and shows a diffuse growth pattern. "In a kinome, CRISPR‐Cas9 knockout screen in which kinases in malignant pleural mesothelioma (MPM) cancer cells were targeted WEE1, AURKA, MPP3, MAP3K12, DGKD and SPEG could be identified as candidate genes." (PMID 40242936, 2025).
multiple myeloma (1 paper, 2021). "We find that CD38-inhibitors such as daratumumab, licensed to treat multiple myeloma, and MAP3K12-inhibitors such as CEP-1347 may increase PD risk." (PMID 34930919, 2021).
non-Hodgkin lymphoma (1 paper, 2021). Distinct from Hodgkin lymphoma both morphologically and biologically, non-Hodgkin lymphoma (NHL) is characterized by the absence of Reed-Sternberg cells, can occur at any age, and usually presents as a localized or generalized lymphadenopathy associated with fever and weight loss. "Amplification of the MAP3K12 locus has been reported in non-Hodgkin’s lymphomas." (PMID 34874980, 2021).
cancer (7 papers, 2016 to 2025). A tumor composed of atypical neoplastic, often pleomorphic cells that invade other tissues. "Three additional predicted cancer driver mutations (EPHA7, MAP3K12, and PCSK5) were identified that were acquired during the transformation of non‐malignant MCF10A cells to malignant DCIS.com cells that could also be implicated in the cell‐context dependency of SOX11 in promoting invasion." (PMID 28707729, 2017).
tumor (5 papers, 2008 to 2023). "Both, proapoptotic BCL-2 or MAP kinase pathway members (BIK, BAK1, MAP3K12, and MAPK9) and proliferation-associated tumor drivers (FOS, HOXA3, and POLR2B) had an increased gene expression." (PMID 35778418, 2022). "We found that MAP2K6, MAP3K5, MAP3K9, MAP3K12, RPS6KA2, RPS6KA5, and STAT1 were lowly expressed in tumor tissues; However, NFKB1, RAC1, SHC1, and TRAF2 are highly expressed compared to normal tissues." (PMID 36969076, 2023).
MAP3K12 also shares sentences with these, for which no sentence is quoted: breast carcinoma (1 paper); glaucoma (1); hepatocellular carcinoma (1); infection (1); lung carcinoma (1); lung squamous cell carcinoma (1); neurodegenerative disease (1); Parkinson disease (1); Salmonella Infections (1); α thalassemia (1).